NLRC3 (NLR family CARD domain containing 3)
Diseases named in the same sentence as NLRC3 in open-access papers (continued):
Sharing a sentence is not in itself a finding about the gene and the disease.
lung carcinoma (1 paper, 2024). "Future research endeavors should prioritize elucidating the intricate mechanisms by which NLRC3 regulates the cGAS-STING pathway in lung cancer and leverage this knowledge to optimize therapeutic strategies." (PMID 39439455, 2024). "For instance, in lung cancer patients, low NLRC3 expression correlates with poor prognosis, implying a potential tumor-suppressive role for NLRC3 in disease progression." (PMID 39439455, 2024). "This review has highlighted the burgeoning potential of NLRC3 as a promising target for lung cancer immunotherapy, summarizing recent research progress in this exciting field." (PMID 39439455, 2024). "Despite these challenges, NLRC3-based immunotherapy strategies remain a beacon of hope in the fight against lung cancer." (PMID 39439455, 2024). "This highlights the multifaceted nature of NLRC3 and its profound importance in shaping anti-tumor immunity in lung cancer." (PMID 39439455, 2024). "Through sustained research efforts and continued innovation, scientists strive to translate the promise of NLRC3-based immunotherapy into tangible clinical benefits for lung cancer patients, ultimately improving patient outcomes and advancing the field." (PMID 39439455, 2024). "The development of pharmaceutical interventions and gene therapy strategies targeting NLRC3 presents a promising avenue for the creation of novel therapeutic options for individuals afflicted with lung cancer." (PMID 39439455, 2024). "Preclinical studies have provided compelling evidence that NLRC3 inhibition can significantly augment the efficacy of immune checkpoint inhibitors, leading to improved treatment outcomes in preclinical models of lung cancer." (PMID 39439455, 2024). "NLRC3, a negative regulator, exhibits considerable potential in the realm of lung cancer immunotherapy by virtue of its profound impact on the immune response intensity, primarily through its regulatory effects on the cGAS-STING pathway." (PMID 39439455, 2024). "Preclinical studies have demonstrated that inhibiting NLRC3 can significantly augment the efficacy of immune checkpoint inhibitors, leading to improved treatment outcomes in lung cancer." (PMID 39439455, 2024). "A deeper understanding of the molecular mechanisms and functional intricacies of NLRC3 could pave the way for more precise and effective therapeutic strategies, further improving treatment outcomes and survival rates for lung cancer patients." (PMID 39439455, 2024). "NLRC3, acting as a negative regulator of the cGAS-STING pathway, holds significant promise as a therapeutic target for lung cancer immunotherapy." (PMID 39439455, 2024). "This comprehensive review endeavors to elucidate the molecular and genetic structures of NLRC3, its role within the immune system, and its interaction with the cGAS-STING pathway, with a particular emphasis on its potential applications in lung cancer immunotherapy." (PMID 39439455, 2024). "Existing research underscores NLRC3's capacity to mitigate excessive immune responses via the negative regulation of the cGAS-STING pathway, thus underscoring its significant regulatory role in lung cancer immunotherapy." (PMID 39439455, 2024).
mucinous ovarian carcinoma (1 paper, 2024). An invasive malignant neoplasm that arises from the ovary and is characterized by the presence of malignant epithelial cells that contain intracytoplasmic mucin and may resemble the epithelial cells of the endocervix or gastrointestinal tract.
multiple sclerosis (1 paper, 2021). A progressive autoimmune disorder affecting the central nervous system resulting in demyelination. "Therefore, it could be possible that a deficiency in NLRC3 expression within the human population could predispose individuals with low CD4+ T‐cell NLRC3 expression to develop multiple sclerosis (MS) or MS‐related disorders." (PMID 33682108, 2021).
non-small cell lung carcinoma (1 paper, 2023). A group of at least three distinct histological types of lung cancer, including non-small cell squamous cell carcinoma, adenocarcinoma, and large cell carcinoma. "We used three single-cell RNA-seq datasets (NSCLC_EMTAB6149, NSCLC_GSE127465, and NSCLC_GSE139555) obtained from the TISCH database containing data for non-small cell lung cancer to analyze the expression of NLRC3 in tumor microenvironment (TME)-related cells." (PMID 36808166, 2023).
Obesity (1 paper, 2024). Accumulation of substantial excess body fat. "For example, the MICs of people with obesity are desensitized to STING activation as saturated fatty acids inhibit STING activation by activating NLRC3." (PMID 38339107, 2024).
osteoporosis (1 paper, 2024). A condition of reduced bone mass, with decreased cortical thickness and a decrease in the number and size of the trabeculae of cancellous bone (but normal chemical composition), resulting in increased fracture incidence. "We performed this study to investigate NLRC3’s role in regulating Th17 cell activation as well as osteoclastogenesis during osteoporosis, and the associated molecular mechanisms." (PMID 38436712, 2024). "Furthermore, we initiated to reveal the underlying molecular pathways mediating NLRC3’s effect on Th17 cells during osteoporosis." (PMID 38436712, 2024). "Altogether, our evidenced results indicate that NLRC3 can be used as a potential target for osteoporosis treatment." (PMID 38436712, 2024). "Findings from our study have favored NLRC3 as the candidate therapeutic target for managing dysregulation of the adaptive immunity inducing osteoporosis." (PMID 38436712, 2024). "In osteoporosis, NLRC3 attenuated TNFα+ Th17 cell accumulation in the bone marrow." (PMID 38436712, 2024). "Also, NLRC3 attenuates TNFα+ Th17 cell accumulation into the bone marrow in osteoporosis." (PMID 38436712, 2024). "However, osteoporosis (OP) development was aggravated without affecting bone marrow macrophage (BMM) osteoclastogenesis in NLRC3-deficient ovariectomized (OVX) mice." (PMID 38436712, 2024). "The obtained findings have suggested the potential of NLRC3 to attenuate osteoclastogenesis, thus promoting CD4+ T cell functions and their ability to recruit CD11bhiLy6Chi inflammatory monocytes into the bone marrow; thereby, restricting osteoporosis progression." (PMID 38436712, 2024).
reovirus infection (1 paper, 2022). "A similar pattern of expression was for NLRC3 and NLRC5 in channel catfish (Ictalurus punctatus), in which the genes expression was induced significantly in liver by hemorrhage reovirus infection." (PMID 36119061, 2022).
Senile plaques (1 paper, 2020). Senile plaques are extracellular deposits of amyloid in the gray matter of the brain. "Hippocampal slices from the Aβ + NLRC3 group exhibited a lower senile plaques burden compared with both Aβ and Aβ + PBS groups." (PMID 33425209, 2020).
Thrombocytopenia (1 paper, 2021). A reduction in the number of circulating thrombocytes. "In summary, the results we report here demonstrate that after inoculated with HTNV through the intraperitoneal route, Nlrc3−/− mice develop weight loss, thrombocytopenia, renal dysfunction, and hemorrhage." (PMID 34335602, 2021). "This study demonstrated that Nlrc3−/− mice model resembles systematic injury observed in patients with HFRS, characterized by thrombocytopenia, renal tubule dilation, and hemorrhage." (PMID 34335602, 2021).
tuberculosis (1 paper, 2018). A chronic, recurrent infection caused by the bacterium Mycobacterium tuberculosis. "Our findings also suggested that NLRC3 serves as a potential target for therapeutic intervention against tuberculosis." (PMID 30133544, 2018). "Our findings also suggested that NLRC3 serves as a potential target for the development of therapeutic intervention against tuberculosis." (PMID 30133544, 2018).
infection (13 papers, 2015 to 2025). The state of being infected such as from the introduction of a foreign agent such as serum, vaccine, antigenic substance or organism. "Together, these results indicate that the Nlrc3−/− mice are more susceptible to intraperitoneal infection of HTNV." (PMID 34335602, 2021). "The genes specifically downregulated over the course of infection by Fasciola miRNAs included Nod1, E2f1, Tnfaip3 and Cdk6 at 6 hrs, and Jam3, Vegfa, Nod1, Uvrag and Nlrc3 at 18 hrs." (PMID 39344634, 2024). "In black rockfish intestine following E. tarda infection, up-regulated NLRC3 genes were found at all the time points post infection, with an increasing trend of up-regulation versus down-regulation occurring as the time post infection increased." (PMID 37964222, 2023). "In spleen following A. salmonicida infection, the number of up-regulated NLRC3 genes was similar to the number of down-regulated genes at each time point post-infection." (PMID 37964222, 2023). "In the liver, another well-recognized immune organ, a large proportion of NLRC3 genes were significantly up-regulated at all time points post infection in black rockfish during A. salmonicida challenge." (PMID 37964222, 2023). "The regulatory effect of NLRC3 on the body’s anti-infection immunity to DNA viruses is mainly focused on innate immunity." (PMID 36341336, 2022). "NLRC3 mediates immune evasion of Mycobacterium tuberculosis (M. tuberculosis) after infection in vivo, while downregulation of NLRC3 expression has a protective effect on M. tuberculosis infection." (PMID 36341336, 2022). "Nlrc3−/− mice developed weight loss, renal hemorrhage, and tubule dilation after HTNV infection, recapitulating many clinical symptoms of human HFRS." (PMID 34335602, 2021). "NLRC3 has emerged as a negative regulator of inflammatory signaling and is known to suppress the innate immune response during pathogen infection." (PMID 30133544, 2018). "Our transcriptomic profiling demonstrates that macrophages treated with H. pylori have significantly repressed Nlrc3 and Nlrx1 transcripts, especially early post-infection; a finding further validated by qRT-PCR along with sustained and late-wave genes." (PMID 26367386, 2015). "Additionally, NLRC3 diminishes antiviral immunity and triggers inflammatory responses in the primary brain cells of groupers after infection with nervous necrosis virus." (PMID 39859554, 2025). "Moreover, the immune-suppressive signals, such as suppression of IL21R on STAT3, PI3K mediated inhibition of inflammation by dopamine upon infection, as well as the inhibition of NLRC3 on STING during a steady state." (PMID 34290708, 2021). "Our results showed that HTNV infection led to elevated cytokine production, including CXCL-1, CCL-5, IL-6, IL-12, TNF-α, and IFN-γ in Nlrc3−/− mice, and the levels of these cytokines peaked at 6 or 9 dpi; in comparison, WT mice had weaker cytokine responses throughout the infection process." (PMID 34335602, 2021). "However, the exact role of NLRC3 and the mechanisms underlying its effects on CD4+ T cell activation and differentiation remain unclear, particularly during in vivo pathogen infection." (PMID 30133544, 2018). "CD4+ T cells isolated from the lungs of Nlrc3-/- mice showed stronger expression of intracellular IFN-γ, TNF-α and IL-17A after restimulation than that showed by CD4+ T cells isolated from lungs of WT mice at 3 weeks post-infection (w.p.i.)." (PMID 30133544, 2018). "In teleost, the NLRC3 of grouper acts as a host factor that negatively regulated the antiviral immune response to facilitate nervous necrosis virus replication; however, zebrafish NLRC3-like protein could interact with SVCV, and has positive regulatory function during SVCV infection." (PMID 37627029, 2023).
tumor (13 papers, 2015 to 2025). "Precisely modulating NLRC3 activity holds the potential to amplify anti-tumor immune responses while simultaneously mitigating the risk of tissue damage that can arise from excessive immune reactions." (PMID 39439455, 2024). "In cluster 1 (pyr-0), genes, including GPR171 and NLRC3, regulate pathways related to tumor occurrence and development, such as cell-substrate adhesion." (PMID 39744500, 2025). "These drugs function by binding to NLRC3, effectively inhibiting its negative regulatory function and unleashing the anti-tumor potential of the cGAS-STING pathway." (PMID 39439455, 2024). "In the field of gene therapy, CRISPR-Cas9 and other cutting-edge gene editing technologies are being employed to knock out or silence the NLRC3 gene, aiming to enhance the immune system's ability to recognize and eliminate tumor cells." (PMID 39439455, 2024). "Concurrently, clinical studies are critical to evaluate the safety and efficacy of NLRC3-based therapies in human patients and to explore personalized treatment approaches tailored to individual patients' tumor and immune profiles." (PMID 39439455, 2024). "In tumor models, NLRC3 knockout mice display enhanced anti-tumor immune responses, suggesting that NLRC3 contributes to tumor immune evasion by regulating the cGAS-STING pathway." (PMID 39439455, 2024). "Our study revealed a significant correlation between the expression of NLRC3 and the tumor immune microenvironment of LUAD." (PMID 36808166, 2023). "This study analyzed both RNA sequencing data and corresponding clinical outcomes obtained from public databases to identify (i) NLRC3 as a tumor suppressor in LUAD and (ii) its predictive value for the likelihood of patient responsiveness to immunotherapy." (PMID 36808166, 2023). "The NLRC3 expression level was also correlated with tumor stage, and its level was significantly higher in early-stage tumors (stage I) than in advanced-stage tumors (stage III)." (PMID 36808166, 2023). "Paired normal and tumor tissues were acquired from each patient and performed by IHC with NLRC3 antibody." (PMID 35145917, 2022). "The tumor-bearing mouse models were also established with NLRC3 over-expressing and knock-down Hepal-6 cells to assess its effect." (PMID 35145917, 2022). "In this study we firstly used the GEO (Gene Expression Omnibus) database and mIHC (multiple immunohistochemical analysis) with TMAs (tumor tissue microarrays) of HCC patients to evaluate NLRC3 levels." (PMID 35145917, 2022). "At last, we established tumor-bearing mouse models in vivo to determine the effect of NLRC3 on CD8+ T cell infiltration by over-expressing or knocking-down the NLRC3 gene." (PMID 35145917, 2022). "The data revealed that CCL5 is expressed in HCC tumor tissues and its expression is significantly correlated with NLRC3 (P<0.0001, R2 = 0.2372)." (PMID 35145917, 2022). "According to the expression of NLRC3 in tumor tissues, patients were classified into NLRC3-high group (n = 147) and NLRC3-low group (n = 64)." (PMID 35145917, 2022). "This study also implies that boosting NLRC3 is a promising strategy to inhibit the development of tumor and thus increase the survival of HCC patients in clinic hospital." (PMID 35145917, 2022). "The expression of NLRC3 increases the infiltration of CD8+ T cells in tumor tissue, enhances survival in HCC patients." (PMID 36341336, 2022). "Univariate analysis showed that the NLRC3 level, together with tumor size, and BCLC stage, contributed to HCC outcome." (PMID 35145917, 2022). "NLRC3 protein levels were investigated by mIHC in HCC tumor tissues on the TMAs, together with CD8 and CD11c infiltration." (PMID 35145917, 2022). "The mRNA expression of cGAS-STING pathway members, except for IFI16 and NLRC3, was significantly related with individual cancer stages and tumor grades in HCC." (PMID 33006365, 2020).
tumor (continued). "Among the genes analyzed, AIM2 and NLRC3 expression was significantly reduced in stage IV CRC compared to the earlier tumor stages." (PMID 26378020, 2015). "Furthermore, it was discovered that the NOD‐like receptor family CARD domain containing 3 (NLRC3)/phosphoinositide 3‐kinase (PI3K)/AKT signaling pathway contributes to green walnut husks‐induced apoptosis in tumor cells." (PMID 41179368, 2025). "The NLRC3 expression level was also correlated with tumor stage." (PMID 36808166, 2023). "This study demonstrated that NLRC3 acts as a tumor suppressor in LUAD." (PMID 36808166, 2023). "Compared with peritumor tissues, NLRC3 expression was reduced in HCC tumor tissues (***P<0.0001)." (PMID 35145917, 2022). "Two independent studies have shown NLRC3 has tumour suppressive roles in IECs." (PMID 34854889, 2021). "Furthermore, we investigated the chemokines that could recruit T cells to tumor, and their relationships with NLRC3 in HCC." (PMID 35145917, 2022). "The synergistic combination of NLRC3 inhibitors, cGAS-STING pathway agonists, and immune checkpoint inhibitors holds particular promise for enhancing anti-tumor immune responses on multiple fronts." (PMID 39439455, 2024). "We therefore propose that upregulation of NLRC3 increases the infiltration of effector immune cells (NK cells and CD8+ T cells), thereby changing a “cold tumor” into a “hot tumor” and driving tumor regression." (PMID 36808166, 2023). "NLRC3 expression was reduced in LUAD, and it was expressed at lower levels in advanced-stage tumors, indicating that NLRC3 downregulation promotes tumor progression." (PMID 36808166, 2023). "This suggests that NLRC3 promotes the CD8+ T cell infiltration in vivo and inhibits the tumor growth." (PMID 35145917, 2022). "We investigated the relationship between NLRC3 levels in cancer tissues and patient prognosis based on histochemical staining of TMA tumor samples, clinicopathological data, and survival data of 211 HCC patients." (PMID 35145917, 2022). "At the same time, it was also confirmed that NLRC3 was positively correlated with CXCL9 (P<0.0001, R2 = 0.2338) expressions in HCC tumor." (PMID 35145917, 2022). "Our study firstly revealed the positive correlations between NLRC3 and CCL5 and CXCL9 expressions in HCC, which explained the mechanisms of NLRC3-related CD8+ T cell infiltration in tumor." (PMID 35145917, 2022). "So NLRC3 high expression represents a novel predictor for positive survival outcomes in HCC patients, and NLRC3 is involved in CD8+ T cell infiltration, which is correlated with increased CCL5 and CXCL9 in TME (tumor microenvironment)." (PMID 35145917, 2022). "Treatment of ApcMin/+Nlrc3−/− mice with a PI3K/mTOR inhibitor reduced organoid-forming capacity, tumour burden and phosphorylation of S6 kinase, indicating a mechanism by which NLRC3 maintains homeostasis and limits tumourigenesis." (PMID 34854889, 2021). "In sum, these results obtained from the TCGA database indicate that across tumor stages, NLRP1, NLRP3, NLRC3, NLRC4 and AIM2 expression in CRC tissues was significantly less than healthy controls." (PMID 26378020, 2015). "NLRC3 showed moderate and strong correlations with CCL5, CXCL9, CXCL10, CXCL11, CXCR3, and CCR5, resulting in an increased recruitment of NK cells, TH1 cells, and CD8+ T cells in tumor tissues." (PMID 36808166, 2023). "Therefore, the next part of the study investigated the relationship between NLRC3 and CD8+ T cell infiltration in liver tumor microenvironments from the perspective of tumor immunology." (PMID 35145917, 2022). "However, the significance of NLRC3 in HCC clinical management and its involvement in tumor immunology remain unclear." (PMID 35145917, 2022).